SDCCAG8 (SHH signaling and ciliogenesis regulator SDCCAG8)
Diseases named in the same sentence as SDCCAG8 in open-access papers:
SDCCAG8 is named in the same sentence as 40 diseases in open-access papers, as found by Europe PMC text mining. Sharing a sentence is not in itself a finding about the gene and the disease. The quoted sentences say what the papers report.
Bardet-Biedl syndrome (13 papers, 2015 to 2024). A ciliopathy with multisystem involvement. "SDCCAG8, also known as BBS16, causes Bardet–Biedl syndrome through the loss of ciliary formation due to the carboxy terminus of the protein product, SDCCAG8, being directly involved in the process." (PMID 36830640, 2023). "Bardet–Biedl Syndrome, one of the major causes of syndromic obesity, and Senior–Loken Syndrome 7 are associated with mutations in SDCCAG8." (PMID 36986146, 2023). "Mutation of Sdccag8 causes diseases such as nephronophthisis, Bardet-Biedl syndrome, and retinal-renal ciliopathy, and it is also often observed in patients with mental retardation, cognitive impairment, and seizures." (PMID 30922366, 2019). "Recessive variants in SDCCAG8 gene were also associated with Bardet-Biedl syndrome and with an increased risk for schizophrenia." (PMID 30853971, 2019). "Mutations in NPHP4 and SDCCAG8 would cause Senior-Loken syndrome and Bardet-Biedl syndrome, these two disorders are characterized by LCA/RP and other systemic features including kidney conditions." (PMID 28456785, 2017). "For SDCCAG8, previous mutation screens focused on obesity in patients with Bardet-Biedl syndrome and revealed frameshift-, nonsense and loss of splicing enhancer mutations." (PMID 26828654, 2016). "Recessive mutations in the SDCCAG8 gene cause a nephronophthisis-related ciliopathy with Bardet-Biedl syndrome-like features in humans." (PMID 27224062, 2016). "Mutations of SDCCAG8 are known to be associated with the human diseases such as nephronophthisis and Bardet-Biedl syndrome (BBS) a rare autosomal recessive ciliopathy with various symptoms, including renal and retinal abnormalities." (PMID 26733777, 2015). "For serologically defined colon cancer antigen 8 (SDCCAG8), recessive mutations in the SDCCAG8 gene can cause a nephronophthisis-related ciliopathy with Bardet-Biedl syndrome-like features, and SDCCAG8 appears to interact with APOL1 to modulate the risk for nondiabetic end-stage kidney disease." (PMID 38898508, 2024). "Mutations in SDCCAG8, encoding the sonic hedgehog (SHH) signaling and ciliogenesis regulator, SDCCAG8, cause Bardet-Biedl Syndrome 16 (BBS16)." (PMID 37872160, 2023). "For example, in family 36, a homozygous deletion c.1444del p.(Thr482Leufs*12) in SDCCAG8 was identified in proband 36‐1 age 10, this gene is known to cause Senior‐Løken syndrome 7 (OMIM #613615) and Bardet–Biedl syndrome 16 (OMIM #615993), two multisystem ciliopathies with RP." (PMID 32783370, 2020). "SDCCAG8 is involved in Bardet-Biedl syndrome; which is a syndromal form of obesity." (PMID 26828654, 2016).
Obesity (11 papers, 2010 to 2023). Accumulation of substantial excess body fat. "Previous studies found that SDCCAG8 causes nephronophthisis type 10, characterized by retinal and renal degeneration, mild intellectual disability, obesity, hypogonadism, and recurrent respiratory infections in humans." (PMID 31537805, 2019). "In sum a strong impact of the detected mutations in TNKS and SDCCAG8 on obesity cannot be derived from our data." (PMID 26828654, 2016). "In addition, we assessed the effect of the markers in 31,182 obese, lean, normal weight, and unselected individuals from population-based samples and showed that the variants near FTO, MC4R, TMEM18, and SDCCAG8 were consistently associated with obesity." (PMID 20421936, 2010). "However, the variants we detected were too infrequent for meaningful obesity association analysis (SDCCAG8 [Thr398Met], TNKS [Pro275Ala], MSRA [Arg6GlufsX88], [Asp142Tyr], [Gly187Ser]) or showed no obesity association (SDCCAG8 [Glu378Asp], TNKS [Gly237Ala]; MSRA [Thr88Met],)." (PMID 26828654, 2016). "Serologically defined colon cancer antigen 8 (SDCCAG8) is an NPHP-RC gene (NPHP10), with patients displaying retinal and renal abnormalities, obesity, learning disabilities, and recurrent respiratory infections." (PMID 29444170, 2018). "Of interest are the variants in/near five genes (PTER, NPC1, MAF, SDCCAG8 and TNKS/MSRA) that had previously been associated with obesity also using samples of individuals who were extremely overweight." (PMID 21935397, 2011). "We observed that genetic variants in or near FTO, MC4R, TMEM18, SDCCAG8, and TNKS/MSRA were robustly associated with early-onset obesity." (PMID 20421936, 2010). "According to variance differences between both groups, we assume that the possible endocrine role of SDCCAG8 could contribute to the development of obesity-related hypertension." (PMID 36010152, 2022). "Nine loci have been associated with extreme obesity at the genome-wide level, five of them influencing BMI / waist circumference as well as risk for extreme obesity (FTO, MC4R, TMEM18, MSRA, NPC1), four loci being more specific of genetic risk for extreme obesity (MAF, PTER, PRL, SDCCAG8)." (PMID 22043164, 2011). "Similarly the odds ratios for the respective obesity risk effect alleles did not vary strongly by group (children and adolescents vs. adults) with point estimates ranging between 1.35–1.45 (FTO), 1.35–1.45 (TMEM18) and 1.10–1.19 (SDCCAG8)." (PMID 20421936, 2010).
schizophrenia (9 papers, 2015 to 2025). A major psychotic disorder characterized by abnormalities in the perception or expression of reality. "A recent EWAS has also linked DNAm of SDCCAG8 with prenatal maternal stressful life events associated with risk of schizophrenia." (PMID 37469193, 2024). "The most significant association with schizophrenia in the DLPFC construct for this subset of genes was increased predicted expression of SDCCAG8—ZTWAS = 6.16, P = 7.21 × 10−10." (PMID 32398653, 2020). "This is particularly important for study of Akt3 function, given that SDCCAG8, a gene also implicated in schizophrenia, flanks Akt3 both in humans and mouse and shares regulatory regions." (PMID 28467426, 2017). "SDCCAG8 is highly expressed in the human fetal brain during development, and alterations in SDCCAG8 expression have been suggested as a candidate pathway underlying risk for schizophrenia and related cognitive deficits." (PMID 37469193, 2024). "Consistently, mutations in PCM1 were associated with schizophrenia 75, 76, 77, and PCM1, Hook3, DISC1, and SDCCAG8 were implicated in maintaining neural progenitor cells and neuronal migration during cortical development." (PMID 31023719, 2019). "For five loci shared between openness and schizophrenia (BRINP2, SDCCAG8, PSORS1C1, DGKI and AK093940), the effect directions were concordant." (PMID 28533504, 2017).
ciliopathy (7 papers, 2013 to 2025). A genetic disorder of the cellular cilia or the cilia anchoring structures, the basal bodies, or of ciliary function. "SDCCAG8 was identified as a syndromic ciliopathy-associated gene in 2010, and was further proven to be a satellite protein due to its colocalization and interaction with PCM1." (PMID 40801568, 2025). "Serologically defined colon cancer autoantigen protein 8 (SDCCAG8) is classified as a ciliopathy-associated gene, and the SDCCAG8 protein localizes to centriolar satellites and the connecting cilium in the transition zone." (PMID 40801568, 2025). "Serologically defined colon cancer autoantigen protein 8 (SDCCAG8), which encodes a protein containing eight coiled-coil (CC) domains, has been associated with syndromic ciliopathies and male infertility." (PMID 40801568, 2025). "Future studies should focus on whether satellite-targeted interventions can rescue flagellar defects in SDCCAG8-deficient models, offering potential therapeutic avenues for ciliopathy-associated infertility." (PMID 40801568, 2025). "Mutations in SDCCAG8 were described in patients with nephronophthisis-related ciliopathies; even though the clinical features of those patients include ID, a feature that is present in our patient, the alterations causing disease in those cases are associated with a recessive model of inheritance." (PMID 30853971, 2019). "SLS is a genetically heterogeneous renal–retinal ciliopathy associated with multiple ciliopathy-related genes, including NPHP1, NPHP4, IQCB1, and SDCCAG8." (PMID 40725491, 2025). "The C-terminal truncated mutation in humans and mice leads to similar syndromic ciliopathy phenotypes, and the severity of the phenotypes was negatively proportional to the hypomorphic strength of the Sdccag8 mutations, Y236X and E451GfsX467." (PMID 40801568, 2025).
nephronophthisis (5 papers, 2016 to 2021). Progressive tubulointerstitial injury, inherited in an autosomal recessive pattern, caused by mutations in genes involved in ciliary function, which may result in an end stage renal failure. "Sdccag8 knockout mice develop late-onset nephronophthisis and severely increased BP42." (PMID 31537805, 2019).
Senior-Loken syndrome (5 papers, 2016 to 2025). Senior-Loken syndrome (SLSN) is a very rare autosomal recessive oculo-renal disease characterized by the association of nephronophthisis (NPHP), a chronic kidney disease, with retinal dystrophy. "In our cohort of 17 Korean patients with genetically confirmed Senior-Loken syndrome (SLS), four causative genes were identified: NPHP1 (35.3%), NPHP4 (29.4%), IQCB1 (29.4%), and SDCCAG8 (5.9%)." (PMID 40725491, 2025).
Cognitive impairment (3 papers, 2015 to 2024). Abnormal cognition is characterized by deficits in thinking, reasoning, or remembering. "Patients with mutations in SDCCAG8 often exhibit neurodevelopmental disorders, including mental retardation, cognitive impairment, and seizures, suggesting a roles for SDCCAG8 in brain development." (PMID 26733777, 2015).
retinal ciliopathy (3 papers, 2024 to 2025). "Additionally, we found that SDCCAG8 (NPHP10), a retinal ciliopathy-associated protein, exhibits specific localization to the end of both BB and DC in rods and cones." (PMID 38979372, 2024). "Additionally, we found that Serologically defined colon cancer antigen 8 (SDCCAG8, or NPHP10), a retinal ciliopathy–associated protein, exhibits specific localization to the end of both BB and DC in rods and cones." (PMID 39898911, 2025).
Hypertension (2 papers, 2019 to 2022). The presence of chronic increased pressure in the systemic arterial system. "This evidence leads us to hypothesize that dysregulation of cg06882058 may affect expression of SDCCAG8 and thereby cause hypertension and contribute to CVD risk." (PMID 31537805, 2019).
Blindness (1 paper, 2025). Blindness is the condition of lacking visual perception defined as a profound reduction in visual perception. "The patient with SDCCAG8 mutation exhibited both end-stage renal disease and congenital blindness due to LCA." (PMID 40725491, 2025).
cervical cancer (1 paper, 2019). A primary or metastatic malignant neoplasm involving the cervix. "In addition, SDCCAG8 was suggested as a biomarker to classify cervical cancer patients, who can benefit from radiotherapy only treatment, from those who would need both radiotherapy and chemotherapy." (PMID 30922366, 2019).
colon cancer (1 paper, 2016). "SDCCAG8 (up-regulated 86-fold) organizes the centrosome and is related to a colon cancer autoantigen." (PMID 26847345, 2016).
end-stage renal disease (1 paper, 2025). "The patient with an SDCCAG8 (NPHP10) mutation exhibited severe dual-organ involvement with end-stage renal disease and congenital blindness due to LCA." (PMID 40725491, 2025).
gastric cancer (1 paper, 2019). A primary or metastatic malignant neoplasm involving the stomach. "Over-expression of SDCCAG8 was also observed in gastric cancer cells of patients with poor survival rates, and in diffuse-type gastric cancer cells, which are non-cohesive and poorly differentiated." (PMID 30922366, 2019).
glaucoma (1 paper, 2021). Increased pressure in the eyeball due to obstruction of the outflow of aqueous humor. "Three of them, ROR2, SDCCAG8, and FXYD6, are involved in molecular pathways that might have the slightest relation to glaucoma and are of potential interest for further investigations into their potential roles in glaucoma-related mechanisms." (PMID 34834521, 2021).
head and neck cancer (1 paper, 2019). A primary or metastatic malignant neoplasm affecting the head and neck. "In summary, we have demonstrated that SOX11 promotes head and neck cancer progression via the regulation of SDCCAG8." (PMID 30922366, 2019).
head and neck squamous cell carcinoma (1 paper, 2024). A squamous cell carcinoma that arises from any of the following anatomic sites: lip and oral cavity, nasal cavity, paranasal sinuses, pharynx, larynx, and salivary glands. "recently established the ability of Sox11 to regulate SDCCAG8 and to promote thereby head and neck squamous cell carcinoma (HNSCC) progression." (PMID 39039706, 2024).
infertile (1 paper, 2025). "To further characterize the infertile phenotypes of Sdccag8mut/mut males in detail, we used hematoxylin and eosin (H&E) and IF staining to determine the morphology of seminiferous tubules in Sdccag8+/+, Sdccag8mut/mut, and Sdccag8mut/+ mice." (PMID 40801568, 2025).
male infertility (1 paper, 2025). The inability of the male to effect fertilization of an ovum after a specified period of unprotected intercourse. "A C-terminal truncated mutation (c.1351–1352insG) in Sdccag8 led to male infertility and a typical MMAF phenotype in male mice with defects in sperm head shaping and manchette formation." (PMID 40801568, 2025). "To further characterize the SDCCAG8-associated male infertility and to explore the underlying molecular mechanisms, in the present study, we first identified that SDCCAG8 is localized to the centrosomal region and manchette in spermatids." (PMID 40801568, 2025). "Taken together, this Sdccag8 mutation results in a reduced sperm count and motility, morphological abnormalities of the sperm head and flagella, as well as dysregulated sperm flagellar proteins, which collectively account for the male infertility in mice." (PMID 40801568, 2025). "By characterizing an Sdccag8 mutant mouse model carrying a truncation (c.1351–1352insG), we demonstrate that loss of SDCCAG8’s C-terminal CC domains 5–8 causes severe male infertility characterized by MMAF phenotypes, aberrant manchette organization, and defective nuclear elongation." (PMID 40801568, 2025). "The homozygous Sdccag8 mutant mice exhibit male infertility characterized by multiple morphological abnormalities of the flagella (MMAF) and dysmorphic structures in the sperm manchette." (PMID 40801568, 2025). "While male infertility was observed exclusively in the Sdccag8 mutant mice in this study, and the phenotypes are highly similar between mice and humans carrying the same mutation, direct evidence linking SDCCAG8 mutations to human MMAF is absent." (PMID 40801568, 2025). "Therefore, we hypothesize that CC5–7 may constitute a functional module of SDCCAG8, and mutations that disrupt the integrity of CC5–7 may contribute to male infertility and flagellum defects in humans." (PMID 40801568, 2025). "However, there are no further reports about SDCCAG8 and male infertility." (PMID 40801568, 2025).
opioid dependence (1 paper, 2020). "Other studies have sought to separate opioid use from opioid dependence, and have thus far identified SNPs associated with SDCCAG8, SLC30A9, and BEND461." (PMID 32917924, 2020).
ovarian carcinoma (1 paper, 2009). A malignant neoplasm originating from the surface ovarian epithelium. "Autologous antibody responses to SDCCAG8 has been reported in colon and ovarian cancers." (PMID 19832977, 2009).
polydactyly (1 paper, 2022). A disease characterized by the presence of polydactyly, including syndromic and non-syndromic forms. "Similar to previous reports, polydactyly was not present in individuals with SDCCAG8, suggesting increased awareness of the importance of genetic testing for BBS in children with severe CKD without the primary feature of polydactyly." (PMID 35112343, 2022).
thyroid diseases (1 paper, 2023). "Novel TSH sentinel variants associated with thyroid diseases also implicated relatively understudied putative causal genes, such as SPPL3 and SDCCAG8." (PMID 37872160, 2023).
kidney disease (3 papers, 2022 to 2024). "Biological annotation found evidence for three novel decline-associated loci to capture common-variant-effects for genes of rare Mendelian kidney diseases (SDCCAG8, RRAGD, and MUC1), additional to the two such genes in known eGFR-decline loci (UMOD, PRKAG2)." (PMID 39567532, 2024). "The first replicated genotype-phenotype association was established for BBS16 (SDCCAG8), which is associated with more penetrant early-onset kidney disease and absence of polydactyly/brachydactyly." (PMID 39085583, 2024).
cancer (2 papers, 2019 to 2025). A tumor composed of atypical neoplastic, often pleomorphic cells that invade other tissues. "Although there has been clear evidence of SDCCAG8 in regulating cellular functions (e.g., cell cycle, mitotic G2-G2/M phases, recruitment of centrosome proteins, etc.), the underlying mechanisms of SDCCAG8 in cancers, particularly in HNSCC, are largely unknown." (PMID 30922366, 2019). "Recent studies have demonstrated that SDCCAG8 was up-regulated in human lung cells with over-expressed MASPIN playing a role in the invasion of cancer cells." (PMID 30922366, 2019). "However, knockdown of SDCCAG8 expression did not significantly alter the expression of SOX11 in the cancer cells." (PMID 30922366, 2019).
tumor (2 papers, 2019 to 2023). "Sdccag8 is a protein coding gene that has been identified as a tumor antigen with various tumor associations." (PMID 30922366, 2019).
SDCCAG8 also shares sentences with these, for which no sentence is quoted: respiratory infections (2 papers); autistic spectrum disorder (1); Bardet-Biedl syndrome 16 (1); cystic kidney disease (1); genetic disease (1); Hydrocephalus (1); hypogonadism (1); Intellectual disability (1); learning disabilities (1); nephronophthisis 15 (1); Nephropathy (1); neurodevelopmental disorder (1); neuropathies (1); sarcopenia (1).